BAIAP2L2 (BAR/IMD domain containing adaptor protein 2 like 2)
Description:
Phosphoinositides-binding protein that induces the formation of planar or gently curved membrane structures. Binds to phosphoinositides, including to phosphatidylinositol 4,5-bisphosphate (PtdIns(4,5)P2) headgroups. There seems to be no clear preference for a specific phosphoinositide (By similarity).
Synonyms: Pinkbar; FLJ22582
Tractability: Antibody: UniProt places it where antibodies can reach, with high confidence; its Gene Ontology location is reachable by antibodies, with medium confidence.
Gene: Protein-coding gene on chromosome 22 (38,084,652 to 38,111,015, reverse strand). Ensembl gene ENSG00000128298.
Subcellular location: Cell membrane; Cell junction; Cytoplasmic vesicle membrane
Pathways (Reactome):
Signal Transduction: RHOF GTPase cycle
Gene Ontology:
Molecular function: phospholipid binding
Biological process: actin crosslink formation; actin filament bundle assembly; membrane organization; positive regulation of actin filament polymerization; plasma membrane organization
Cellular component: cell-cell contact zone; clathrin complex; vesicle membrane; cytosol; anchoring junction; cytoplasmic vesicle membrane; plasma membrane
Genetic constraint (gnomAD): Loss-of-function variants: 64 observed, 53.67 expected, observed/expected ratio (o/e) 1.19, 90% interval 0.97 to 1.47. The synonymous counts are far from expectation, so gnomAD's model fits this gene poorly and the ratio says little. Missense variants: 800 observed, 661.66 expected, observed/expected ratio (o/e) 1.21, 90% interval 1.14 to 1.28. Synonymous variants: 335 observed, 265.64 expected, observed/expected ratio (o/e) 1.26, 90% interval 1.15 to 1.38.
Homologues: Orthologues: macaque BAIAP2L2 (97% identical), chimpanzee BAIAP2L2 (97% identical), mouse Baiap2l2 (91% identical), dog BAIAP2L2 (88% identical), pig BAIAP2L2 (88% identical), guinea pig BAIAP2L2 (74% identical), rat Baiap2l2 (70% identical), tropical clawed frog baiap2l2 (51% identical), zebrafish baiap2l2b (35% identical), zebrafish baiap2l2a (35% identical), Drosophila melanogaster IRSp53 (24% identical). Paralogues in human: BAIAP2L1 (29% identical), BAIAP2 (27% identical).
Diseases named in the same sentence as BAIAP2L2 in open-access papers:
BAIAP2L2 is named in the same sentence as 38 diseases in open-access papers, as found by Europe PMC text mining. Sharing a sentence is not in itself a finding about the gene and the disease. The quoted sentences say what the papers report.
lung carcinoma (5 papers, 2020 to 2023). "Although BAIAP2L2 was associated with the development of various cancers, including osteosarcoma, gastric cancer, Prostate Cancer and lung cancer." (PMID 36338652, 2022). "The expression level of BAIAP2L2 has been shown to be a biomarker and potential therapeutic target for lung cancer." (PMID 38001569, 2023). "Upregulation of BAIAP2L2 was detected in various lung cancer cell lines and was deemed a novel biomarker and potential therapeutic target for LUAD." (PMID 36338652, 2022). "BAIAP2L2 was up-regulated in lung adenocarcinoma tissues and various lung cancer cell lines, and overexpression of BAIAP2L2 can promote the proliferation and growth of lung adenocarcinoma cells." (PMID 32547947, 2020). "Previous studies have revealed that BAIAP2L2 has predictive value in prostate and lung cancers." (PMID 37248248, 2023).
hearing loss (4 papers, 2020 to 2022). "Mutations of other genes also lead to loss of the shorter stereocilia associated with hearing impairment, for example the Baiap2l2 mutant and the Clrn2 mouse mutant." (PMID 35727972, 2022). "A heterozygous variant of BAIAP2L2 was identified as the candidate cause for AD inheritance mode hearing loss in family 1427." (PMID 35248088, 2022). "An additional five genes have not previously been associated with human hearing loss but are known to cause hearing loss or cochlear development when mutated in mice: SYNJ2, RPGRIP1L, BAIAP2L2, TUB, and RBL2." (PMID 32986727, 2020).
gastric cancer (3 papers, 2022 to 2025). A primary or metastatic malignant neoplasm involving the stomach. "Previous studies have demonstrated that BAIAP2L2 is overexpressed in gastric cancer and associated with metastasis, whereby knockdown of BAIAP2L2 suppresses the activation of the Wnt signaling pathway, consequently inhibiting gastric cancer cell proliferation and metastasis." (PMID 40356901, 2025). "BAIAP2L2 promotes gastric cancer cell proliferation and metastasis via activation of AKT/mTOR and Wnt3α/β-catenin pathways, while serving as a prognostic marker in non-small cell lung cancer patients with low PD-1 and EGFR expression." (PMID 40356901, 2025). "BAIAP2L2 is an epithelial-specific BAR domain protein involved in multiple cancers, including gastric cancer, osteosarcoma, and prostate cancer." (PMID 38001569, 2023).
osteosarcoma (3 papers, 2021 to 2024). A usually aggressive malignant bone-forming mesenchymal neoplasm, predominantly affecting adolescents and young adults. "Again, we identified nine genes related to differences in immune cell infiltration in osteosarcoma, four of which are SORBS2, BAIAP2L2, SNAPC3 and ZDHHC21 with low abundances and they have higher disease-free survival probability than the group with high abundances." (PMID 34922489, 2021).
prostate carcinoma (3 papers, 2020 to 2025). A carcinoma that arises from epithelial cells of the prostate gland. "We used univariate and multivariate Cox regression analysis to identify seven prognostic signatures for prostate cancer patients, including BCO1, BAIAP2L2, C7, AP000844.2, ASB9, MKI67P1, TMEM272." (PMID 32547947, 2020).
deafness (2 papers, 2021 to 2023). An inherited or acquired condition characterized by the complete loss of the ability to hear from one or both ears. "In mice, mutations of the homologous gene Baiap2l2 were associated with alterations in hair cell transduction and deafness while the human locus BAIAP2L2 is associated with suppression of the estrogen-mediated S–phase entry pathway in cell cycle." (PMID 37165447, 2023).
liver cancer (2 papers, 2022 to 2025). An epithelial or non-epithelial malignant neoplasm that arises from the liver. "The findings revealed that mRNA SLC16A3 and BAIAP2L2, which are highly expressed in liver cancer tissues, are associated with the upregulation of eccDNA SLC16A and BAIAP2L2, respectively." (PMID 41009369, 2025). "More importantly, quantitative real-time polymerase chain reaction was used to verify BAIAP2L2 expression in a liver cancer cell line and a normal cell line." (PMID 36338652, 2022). "By comprehensive analysis of the expression and prognosis of BAIAP2L2 across cancers, we found that BAIAP2L2 was overexpressed in LIHC and was closely associated with poor prognosis of liver cancer patients, implying its importance in predicting the clinical outcome of LIHC." (PMID 36338652, 2022). "Furthermore, Cox regression analysis showed that high BAIAP2L2 expression was an independent risk factor for OS and DFS in patients with liver cancer." (PMID 36338652, 2022). "In addition, we examined the protein level of BAIAP2L2 in LIHC using HPA and discovered that BAIAP2L2 was overexpressed in liver cancer." (PMID 36338652, 2022). "However, the relationship between BAIAP2L2 and liver cancer has not been reported." (PMID 36338652, 2022). "However, no studies have reported the relationship between BAIAP2L2 and liver cancer." (PMID 36338652, 2022).
melanoma (2 papers, 2017 to 2024). A malignant, usually aggressive tumor composed of atypical, neoplastic melanocytes. "Indeed, all genes associated with nevus count or cutaneous nevi in cluster 6 (MTAP, TUBBP1, PLA2G6, ERVFRD.3, TMEM184B, BAIAP2L2) were only associated with melanoma." (PMID 38308491, 2024).
lymphoma (1 paper, 2020). A malignant (clonal) proliferation of B- lymphocytes or T- lymphocytes which involves the lymph nodes, bone marrow and/or extranodal sites. "This small in-frame deletion likely does not have a significant effect on protein function, however, there is strong evidence that BAIAP2L1 promotes cell proliferation and inhibits apoptosis and BAIAP2L2 may have a similar role in dog and human lymphoma." (PMID 32857815, 2020).
paraganglioma (1 paper, 2022). A benign or malignant neoplasm arising from paraganglia located along the sympathetic or parasympathetic nerves. "The results showed that a high level of BAIAP2L2 indicated poor DFS in BRCA (p = 0.027), LIHC (p = 0.0061), and testicular germ cell tumors (TGCTs) (p = 0.048) and good DFS in pheochromocytoma and paraganglioma (PCPG) (p = 0.044) and UCEC (p = 0.014)." (PMID 36338652, 2022).
tumor (9 papers, 2015 to 2025). "High BAIAP2L2 expression was associated with histologic grade, pathologic stage, T stage, N stage, M stage, tumor status, Child-Pugh grade and residual tumor." (PMID 36338652, 2022). "Moreover, cross-analysis of the transcriptomic and the Circle-seq data revealed that two genes, SLC16A3 and BAIAP2L2, which were highly expressed in tumor tissues, were related to eccDNAs in the tumor sample and were associated with the survival rate in HCC patient cohorts." (PMID 38001569, 2023). "The absence of xenograft or transgenic mouse experiments limits our ability to fully characterize the role of BAIAP2L2 in tumor growth, progression, and metastasis within the complex tumor microenvironment." (PMID 40356901, 2025). "Clinical validation involved comparing tumor specimens with normal tissues, focusing on BAIAP2L2, which showed significant differential expression and was further examined via immunohistochemical analysis." (PMID 40356901, 2025). "BAIAP2L2 expression was higher in pathologic stage III patients than in stage I patients, and the BAIAP2L2 expression level was higher in the tumor group than in the tumor-free group." (PMID 37248248, 2023). "Simultaneously, the TIMER database showed that the expression of BAIAP2L2 in LIHC was positively correlated with tumor infiltrating cells, including B cells, CD8+ T cells, CD4+ T cells, macrophages, neutrophils and dendritic cells." (PMID 36338652, 2022). "Concurrently, the TIMER database showed that the expression of BAIAP2L2 in LIHC was positively correlated with tumor infiltrating cells, including B cells, DCs, CD8+ T cells, CD4+ T cells and macrophages." (PMID 36338652, 2022). "The TIMER database further showed that the expression of BAIAP2L2 in LIHC was positively correlated with tumor infiltrating cells, including B cells, CD8+ T cells, CD4+ T cells, macrophages, and DCs." (PMID 36338652, 2022). "In PCa cells, BAIAP2L2 may influence tumor initiation and malignant progression through modulation of VEGF signaling and apoptotic pathways." (PMID 40356901, 2025). "Given its significant correlation with tumor progression and patient survival, BAIAP2L2 could potentially enhance patient stratification for aggressive versus indolent PCa, aiding in personalized treatment decisions." (PMID 40356901, 2025). "Future studies should focus on preclinical and clinical investigations to assess the therapeutic feasibility of BAIAP2L2 inhibition, its synergy with existing therapies (e.g., androgen deprivation therapy and immune checkpoint inhibitors), and its impact on tumor microenvironment interactions." (PMID 40356901, 2025). "Therefore, this study explored the expression level and prognostic value of BAIAP2 in HCC and investigated the effects of BAIAP2L2 on tumor immune infiltration, methylation, cuprotosis and drug sensitivity." (PMID 37248248, 2023). "ROC curve analysis showed that BAIAP2L2 expression could distinguish tumor tissues from normal tissues in HCC patients (AUC: 0.897, 95% CI 0.859–0.936)." (PMID 37248248, 2023). "Furthermore, two genes, SLC16A3 and BAIAP2L2, with a higher transcription level in tumor tissues, were related to eccDNAs exclusively detected in three HCC samples and were negatively associated with survival rates in HCC cohorts from public databases." (PMID 38001569, 2023). "Recently, various studies have suggested that BAIAP2L2 may be involved in tumor progression; however, comprehensive bioinformatic analysis of BAIAP2L2 in HCC is rare." (PMID 37248248, 2023). "However, the co-expressed mRNA, BAIAP2L2, was found to be highly expressed in gastric cancer tumors and its expression was significantly correlated with tumor diameter, TNM stage, and lymph node metastasis." (PMID 34532296, 2021).
tumor (continued). "Future investigations should explore potential interactions with key oncogenic pathways in PCa, such as androgen receptor signaling, PI3K/AKT/mTOR pathway, or Wnt/β-catenin signaling, which could provide deeper insights into how BAIAP2L2 influences tumor cell behavior." (PMID 40356901, 2025). "Our work revealed the role of BAIAP2L2 in the progression of HCC, especially in the immune response, tumor microenvironment, and drug resistance, indicating that it could be crucial for developing tailored cancer therapies." (PMID 37248248, 2023). "BAIAP2L2, pituitary tumour-transforming gene 1 (PTTG1) and complement factor H-related 3 (CFHR3) have also been reported to be overexpressed in many types of human cancer and to promote tumour cell angiogenesis, migration and invasion." (PMID 36217206, 2022). "Overall, 8 genes were identified as differentially expressed genes (DEGs) between GC tumor and nontumor tissues (eTable 9 in Supplement 1), with upregulated CDH3 and BAIAP2L2 and downregulated TMED6 also observed in advanced vs mild gastric lesions (eTable 11 in Supplement 1)." (PMID 38809553, 2024).
cancer (7 papers, 2020 to 2025). A tumor composed of atypical neoplastic, often pleomorphic cells that invade other tissues. "In recent years, an increasing number of studies have suggested that BAIAP2L2 is strongly associated with the development of various cancers." (PMID 37248248, 2023). "Previous studies have demonstrated the efficacy of targeting the Wnt/β-catenin pathway in various cancers, suggesting that pharmacological modulation of BAIAP2L2-associated signaling might enhance the efficacy of existing PCa therapies." (PMID 40356901, 2025). "In recent years, the role of BAI1-associated protein 2-like 2 (BAIAP2L2) in the prognosis and immune microenvironment of various cancers has attracted increasing attention." (PMID 36338652, 2022). "Two databases, the Kaplan–Meier Plotter database and LinkedOmics, were utilized to analyze the relationship between BAIAP2L2 expression and patient overall survival (OS) in 33 types of cancer." (PMID 36338652, 2022). "In this study, we comprehensively analyzed the expression profile and prognostic value of BAIAP2L2 in 33 types of cancer, and found that BAIAP2L2 was highly expressed in LIHC." (PMID 36338652, 2022). "In summary, a pan-cancer analysis shows that BAIAP2L2 is highly expressed in LIHC and overexpression of BAIAP2L2 is associated with poor prognosis of LIHC." (PMID 36338652, 2022). "Taken together, the data indicate that BAIAP2L2 may be required for cancer cell migration and invasion in HCC." (PMID 37248248, 2023). "Considering that BAIAP2L2 is dysregulated in a variety of cancers, we wanted to know whether its expression is related to the survival of cancer patients." (PMID 36338652, 2022). "Through pan-cancer analysis, prognostic and immunological value of BAIAP2L2 in LIHC was identified." (PMID 36338652, 2022). "We used TIMER and StarBase database to demonstrate BAIAP2L2 expression in 33 types of human cancer." (PMID 36338652, 2022). "In recent years, studies have suggested that BAIAP2L2 may be involved in the development of human cancer." (PMID 36338652, 2022). "BAIAP2L2 has been proved to be abnormally expressed in cancers." (PMID 36338652, 2022). "It is unknown whether SFXN1 and BAIAP2L2 are involved in the cancer process as few studies on these two genes have been reported." (PMID 32819300, 2020). "We found that the expression of BAIAP2L2 was negatively correlated with the number of DCs, so we inferred that BAIAP2L2 might restrain the activation of DCs and thereby enable the proliferation of cancer cells to further promote the progression of HCC." (PMID 37248248, 2023). "Thus, we investigated whether the abnormal expression of BAIAP2L2 in cancer is related to epigenetics." (PMID 36338652, 2022). "Next, the Kaplan–Meier Plotter database was used to explore the relationship between BAIAP2L2 levels and patient disease-free survival (DFS) in 33 types of cancer." (PMID 36338652, 2022). "In this study, The Cancer Genome Atlas, GTEx, StarBase, UALCAN, TIMER, GEPIA, Human Protein Atlas, Kaplan–Meier Plotter, cBioPortal, LinkedOmics, STRING and BioGPS databases were used to analyze BAIAP2L2 in cancers." (PMID 36338652, 2022). "Seven genes had variants found in the cancers of at least two ‘poor’ responders but in no 'good’ responders: ATRNL1, BAIAP2L2, ZNF384, ST6GALNAC5, ENSCAFG00000030179 (human ortholog: riboflavin kinase RFK), ENSCAFG00000029320, and ENSCAFG00000007370 (human ortholog: immunoglobin IGKV4-1)." (PMID 32857815, 2020).
BAIAP2L2 also shares sentences with these, for which no sentence is quoted: lung adenocarcinoma (3 papers); nevus (2); acute myeloid leukemia (1); breast invasive carcinoma (1); cervical squamous cell carcinoma (1); cholangiocarcinoma (1); diffuse large B-cell lymphoma (1); endocervical adenocarcinoma (1); esophageal carcinoma (1); glioma (1); head and neck squamous cell carcinoma (1); Hearing impairment (1); lung squamous cell carcinoma (1); lymphoid neoplasm (1); mesothelioma (1); non-small cell lung carcinoma (1); ovarian serous cystadenocarcinoma (1); pancreatic adenocarcinoma (1); pheochromocytoma (1); prostate adenocarcinoma (1); skin cutaneous melanoma (1); testicular germ cell tumor (1); thymoma (1); uterine carcinosarcoma (1); uterine corpus endometrial carcinoma (1); uveal melanoma (1).